DCAF6 (DDB1 and CUL4 associated factor 6)
Description:
Ligand-dependent coactivator of nuclear receptors. Enhance transcriptional activity of the nuclear receptors NR3C1 and AR. May function as a substrate receptor for CUL4-DDB1 E3 ubiquitin-protein ligase complex.
Synonyms: ARCAP; NRIP; IQWD1; MSTP055; PC326; 1200006M05Rik
Tractability: PROTAC: ubiquitination databases record sites on it; its protein half-life has been measured.
Gene: Protein-coding gene on chromosome 1 (167,935,783 to 168,076,223, forward strand). Ensembl gene ENSG00000143164.
Subcellular location: Nucleus
Subcellular location (Human Protein Atlas): Nucleoplasm; Cytosol
Pathways (Reactome):
Metabolism of proteins: Neddylation
Gene Ontology:
Molecular function: protein binding; transcription coactivator activity
Biological process: positive regulation of transcription by RNA polymerase II; protein ubiquitination
Cellular component: Cul4-RING E3 ubiquitin ligase complex; nucleoplasm; nucleus; Cul4A-RING E3 ubiquitin ligase complex
Genetic constraint (gnomAD): Loss-of-function variants: 35 observed, 81.84 expected, observed/expected ratio (o/e) 0.43, 90% interval 0.33 to 0.57. The upper end of that interval is the gene's LOEUF score, 0.57, which puts it in group 2 of 6, group 1 being the genes least tolerant of losing a copy. Missense variants: 760 observed, 918 expected, observed/expected ratio (o/e) 0.83, 90% interval 0.78 to 0.88. Synonymous variants: 299 observed, 317.7 expected, observed/expected ratio (o/e) 0.94, 90% interval 0.86 to 1.04.
Homologues: Orthologues: chimpanzee DCAF6 (99% identical), macaque DCAF6 (99% identical), dog DCAF6 (94% identical), pig DCAF6 (93% identical), rat Dcaf6 (87% identical), mouse Dcaf6 (80% identical), guinea pig DCAF6 (68% identical), zebrafish dcaf6 (60% identical), tropical clawed frog dcaf6 (58% identical). Paralogues in human: WDTC1 (20% identical), DCAF8 (17% identical), DCAF8L2 (16% identical), DCAF8L1 (15% identical), DCAF5 (12% identical).
Diseases named in the same sentence as DCAF6 in open-access papers:
DCAF6 is named in the same sentence as 33 diseases in open-access papers, as found by Europe PMC text mining. Sharing a sentence is not in itself a finding about the gene and the disease. The quoted sentences say what the papers report.
limb-girdle muscular dystrophy (3 papers, 2021 to 2024). Limb-girdle muscular dystrophy (LGMD) is a heterogeneous group of muscular dystrophies characterized by proximal weakness affecting the pelvic and shoulder girdles. "The authors concluded that DCAF6 deficiency contributes to the pathogenesis of limb-girdle muscular dystrophy (LGMD) and heart failure, although detailed molecular mechanism remains elusive." (PMID 33731189, 2021). "Interestingly, patients with limb-girdle muscular dystrophy (LGMD) present with severe cardiomyopathy and reduced muscle tissue levels of the CRL4 substrate-recognition receptor, DCAF6." (PMID 38334627, 2024).
tumor (8 papers, 2008 to 2024). "Circ-DCAF6 was found increased in human GC tissues compared to adjacent non-tumor samples." (PMID 33072546, 2020).
psychiatric disorder (1 paper, 2017). A disorder characterized by behavioral and/or psychological abnormalities, often accompanied by physical symptoms. "One possible link between DCAF6, associated with this LD block by eQTL, and susceptibility to psychiatric disorders is that its protein binds NR3C1, of which changes in methylation are linked with childhood abuse." (PMID 27798116, 2017).
DCAF6 also shares sentences with these, for which no sentence is quoted: prostate carcinoma (7 papers); cancer (5); gastric cancer (3); heart failure (2); infection (2); myasthenia gravis (2); pancreatic cancers (2); adenocarcinoma (1); Alport syndrome (1); breast adenocarcinoma (1); breast carcinoma (1); Cerebral visual impairment (1); colon adenocarcinoma (1); Duchenne muscular dystrophy (1); esophageal squamous cell carcinoma (1); germ cell tumor (1); liver cancer (1); lymphoma (1); melanoma (1); motor neuron degeneration (1); muscle disorders (1); ovarian adenocarcinoma (1); ovarian carcinoma (1); pancreatic acinar cell carcinoma (1); pancreatic ductal adenocarcinoma (1); prostate tumors (1); sarcoma (1); skin squamous cell carcinoma (1); squamous cell carcinoma (1); testicular cancer (1).